SOD1 (superoxide dismutase 1)
Diseases named in the same sentence as SOD1 in open-access papers (continued):
Sharing a sentence is not in itself a finding about the gene and the disease.
amyotrophic lateral sclerosis (continued). "Aggregation of Cu–Zn superoxide dismutase (SOD1) is implicated in the motor neuron disease, amyotrophic lateral sclerosis (ALS)." (PMID 33825682, 2021). "Here, indeed, we focus on a mutant model of superoxide dismutase 1, a protein implicated in amyotrophic lateral sclerosis." (PMID 34943155, 2021). "This is of particular interest because a recent study reported that overexpression of MT-1 extends lifespan in a mouse model of amyotrophic lateral sclerosis caused by mutant SOD1." (PMID 33670299, 2021). "Our findings are similar to recent observations in human patients that a loss of function mutation in SOD1 leads to a juvenile neurologic disease distinct from amyotrophic lateral sclerosis." (PMID 33677640, 2021). "Mutations in SOD1 are known to cause recessive degenerative myelopathy in middle-aged dogs with low penetrance and dominant amyotrophic lateral sclerosis in humans with variable age of onset." (PMID 33677640, 2021). "Regarding motor neuron-like cells, we have previously studied Wnt signaling in NSC-34 cells stably expressing a G93A-mutated form of human superoxide dismutase 1 (hSOD1) as a model of amyotrophic lateral sclerosis motor neurons." (PMID 34944540, 2021). "For instance, PARK7 (protein/nucleic acid deglycase DJ‐1) and SOD1 (superoxide dismutase 1) are risk genes for Parkinson's disease and amyotrophic lateral sclerosis, respectively." (PMID 32485097, 2020). "Alterations in the SOD1 expression have been linked to neurodegenerative diseases like amyotrophic lateral sclerosis." (PMID 33081384, 2020). "Another example is the elevated exosomal release of a mutant SOD1 variant to neurons, which fosters disease spreading and has been described for motor neuron pathology in amyotrophic lateral sclerosis (ALS)." (PMID 32605023, 2020). "Mutations to the gene coding for Sod1 are linked to an inherited form of amyotrophic lateral sclerosis (fALS), a neurodegenerative disease resulting in paralysis and eventual death." (PMID 32121118, 2020). "A nonsense mutation in the superoxide dismutase 1 (SOD1) gene was induced by BE3 in amyotrophic lateral sclerosis (ALS) model mice, prolonging survival." (PMID 32651459, 2020). "While there are a multitude of Sod1 mutations linked to the familial form of amyotrophic lateral sclerosis (fALS), characterizations by multiple research groups have been unable to realize strong commonalities among mutants." (PMID 32121118, 2020). "Mutations in the superoxide dismutase 1 (SOD1) gene are related to familial cases of amyotrophic lateral sclerosis (ALS)." (PMID 33276458, 2020). "Normally functioning SOD1 proteins seek out and counteract ROS to protect cellular function, but in Amyotrophic Lateral Sclerosis (ALS), mutated SOD1 contributes to oxidative stress built up in free radicals and mitochondrial dysfunction." (PMID 33510633, 2020). "This line was subsequently crossed with a mouse line expressing mutated G85R SOD1 associated with amyotrophic lateral sclerosis (ALS), and with a mouse line expressing PD-associated A53T α-syn." (PMID 32927676, 2020). "Four genes linked to familial cases of amyotrophic lateral sclerosis were investigated for antisense transcription: SOD1, FUS, TARDBP, and UBQLN2." (PMID 30610612, 2019). "Mutations in more than 80 different positions in superoxide dismutase 1 (SOD1) have been associated with amyotrophic lateral sclerosis (fALS)." (PMID 30622123, 2019). "AON treatment significantly slowed disease progression in a rat model of amyotrophic lateral sclerosis (ALS) caused by a SOD1 mutation, followed, 7 years later, by the first clinical trial of intrathecal delivery of an AON in SOD1 patients." (PMID 30607747, 2019). "A limitation of current research is a significant bias towards models based on superoxide dismutase 1, with uncertainty about generalisability to amyotrophic lateral sclerosis with an underlying TAR DNA binding protein 43 proteinopathy." (PMID 32133457, 2019).
amyotrophic lateral sclerosis (continued). "Macropinocytosis is considered to drive the uptake of prion and SOD1 aggregates associated with neurodegenerative disorders (Creutzfeldt–Jakob disease and amyotrophic lateral sclerosis, respectively) by neuronal cells." (PMID 30980596, 2019). "Amyotrophic lateral sclerosis (ALS) caused by mutation of superoxide dismutase 1 (SOD1), affects various cellular processes and results in the death of motor neurons with fatal defects." (PMID 31771229, 2019). "In humans, for example, a mutation in superoxide dismutase 1 (SOD1), which is a main antioxidant enzyme in cells, has been linked to amyotrophic lateral sclerosis (ALS)." (PMID 31681409, 2019). "A clearer understanding of the Sod1•Ccs1 interaction and mechanism of Ccs1 action is important not only for the fields of copper trafficking and metallo-enzyme function, but also for the realm of Sod1-linked amyotrophic lateral sclerosis (ALS)." (PMID 29950795, 2018). "Mutations associated with amyotrophic lateral sclerosis (ALS) appear in the proteins SOD1, FUS, TDP-43, and OPTN which become misfolded and aggregate." (PMID 30083092, 2018). "So far, little is known about the molecular mechanisms of amyotrophic lateral sclerosis onset and progression caused by SOD1 mutations." (PMID 29431095, 2018). "Autophagy plays a central role in degrading misfolded proteins such as mutated superoxide dismutase 1 (SOD1), which forms aggregates in motor neurons and is involved in the pathogenesis of amyotrophic lateral sclerosis (ALS)." (PMID 29540819, 2018). "Amyotrophic lateral sclerosis is a neurodegenerative disorder and mutations in the superoxide dismutase 1 (SOD1) protein contribute to rapid disease progression." (PMID 30104534, 2018). "Among the familial forms of amyotrophic lateral sclerosis (fALS), 20% are associated with the Cu,Zn-superoxide dismutase (Sod1)." (PMID 28884318, 2018). "Kir4.1 was downregulated cell autonomously in astrocytes derived from amyotrophic lateral sclerosis (ALS) patients with SOD1 mutation." (PMID 29606582, 2018). "Mutations in superoxide dismutase (SOD1) cause amyotrophic lateral sclerosis (ALS), a fatal neurodegenerative disease caused by the progressive loss of motor neurons in the brain and spinal cord." (PMID 29371591, 2018). "As with SAMHD1 loss of function, gain-of-function mutations in SOD1 are associated with neuroinflammation and degeneration, clinically manifesting as amyotrophic lateral sclerosis, which is likely a result of toxic protein aggregates." (PMID 28061811, 2017). "Recently, a complex series of intercrosses and backcrosses between a mutant inbred strain and other inbred strains identified and confirmed a region of chromosome 17 that modifies the expression of a SOD1 mutation linked to amyotrophic lateral sclerosis." (PMID 28280213, 2017). "Mutant SOD1 associated with amyotrophic lateral sclerosis (ALS) bound to bilayer-reconstituted VDAC1 and inhibited its channel conductance." (PMID 30542671, 2017). "Several mutations in SOD1 gene cause amyotrophic lateral sclerosis, probably by altering SOD1 enzymatic activity through the gain of aberrant functions like enhancing catalysis of tyrosine nitration by peroxynitrite." (PMID 28659860, 2017). "Recently, a series of simple intercrosses and backcrosses between a mutant inbred strain and other inbred strains identified and confirmed a region of chromosome 17 that modifies the expression of a SOD1 mutation linked to amyotrophic lateral sclerosis." (PMID 28280213, 2017). "The misfolding and aggregation of SOD1 is linked to inherited, or familial, amyotrophic lateral sclerosis (FALS), a progressive and fatal neurodegenerative disease." (PMID 28472188, 2017). "Understanding how human SOD1 reaches its mature form is critical, as mutations in the SOD1 gene are the root cause of a familial variant of amyotrophic lateral sclerosis (fALS), a fatal neurodegenerative disease." (PMID 28250949, 2017).
amyotrophic lateral sclerosis (continued). "Familial amyotrophic lateral sclerosis can be caused by mutations in superoxide dismutase 1 (SOD1), transactive response DNA-binding protein 43 (TDP-43) and several other genes." (PMID 28820437, 2017). "Ubiquitous expression of mutant Cu/Zn-superoxide dismutase (SOD1) selectively affects motor neurons in the central nervous system (CNS), causing the adult-onset degenerative disease amyotrophic lateral sclerosis (ALS)." (PMID 28205575, 2017). "Over 170 different mutations in the gene encoding SOD1 all cause amyotrophic lateral sclerosis (ALS)." (PMID 28463106, 2017). "Dominant mutations in Cu/Zn-superoxide dismutase (SOD1) gene have been shown to cause a familial form of amyotrophic lateral sclerosis (SOD1-ALS)." (PMID 27556028, 2016). "This transgenic mouse overexpresses mutant human SOD1 and exhibits the age-dependent motor neuronal characteristics associated with amyotrophic lateral sclerosis." (PMID 27478531, 2016). "Third, a missense mutation of SOD1 is associated with the development of amyotrophic lateral sclerosis." (PMID 27755600, 2016). "Mutant human Cu/Zn superoxide dismutase 1 (SOD1) is associated with motor neuron toxicity and cell death in an inherited form of amyotrophic lateral sclerosis (ALS; Lou Gehrig disease)." (PMID 26973652, 2016). "Mutations in superoxide dismutase-1 (SOD1) are a common known cause of amyotrophic lateral sclerosis (ALS)." (PMID 26919046, 2016). "Earlier reports indicated that astrocytes expressing the mutations of superoxide dismutase-1 (SOD1) contribute to motor neuron degeneration in amyotrophic lateral sclerosis." (PMID 27203617, 2016). "For example, mutations in the superoxide dismutase 1 gene lead to the motor neuron disease amyotrophic lateral sclerosis (ALS), while mutations in the SNCA gene encoding for alpha-synuclein protein lead to familial Parkinson’s disease (PD)." (PMID 28725696, 2016). "The pathogenic role of SOD1 mutations in amyotrophic lateral sclerosis (ALS) was investigated using a zebrafish disease model stably expressing the ALS-linked G93R mutation." (PMID 27079797, 2016). "Mutations to the ubiquitous antioxidant enzyme Cu/Zn superoxide dismutase (SOD1) were the first established genetic cause of the fatal, adult-onset neurodegenerative disease amyotrophic lateral sclerosis (ALS)." (PMID 25754173, 2015). "Previously, variants in Superoxide Dismutase 1 (SOD1) causing Amyotrophic Lateral Sclerosis (ALS) were found to destabilize and reduce net charge, suggesting a pathogenic aggregation mechanism." (PMID 25798606, 2015). "Amyotrophic lateral sclerosis is caused by mutations in superoxide dismutase 1 (SOD1) enzyme and vamp-associated protein B/C (VAPB)." (PMID 26089911, 2015). "For example, amyloid-like forms of Aβ and Tau, α-synuclein, huntingtin, FUS/TLS, TDP-43 or SOD1 are linked respectively to Alzheimer's (AD), Parkinson's (PD), Huntington's (Htt) and Amyotrophic Lateral Sclerosis (ALS) diseases." (PMID 25568955, 2015). "In neurons, HSPA8 is known to be involved in the lysosomal degradation of α-synuclein, which accumulates in Parkinson's disease and other neurodegenerative diseases, and in the degradation of the amyotrophic lateral sclerosis-linked mutant SOD1 protein." (PMID 26717306, 2015). "Mutations in superoxide dismutase 1 (SOD1) cause familial forms of amyotrophic lateral sclerosis (fALS)." (PMID 25121776, 2014). "A ketogenic diet has been shown to delay loss of motor performance and loss of spinal cord motor neurons in the SOD1-G93A mouse model of amyotrophic lateral sclerosis (ALS)." (PMID 25127866, 2014). "Dominant mutations in superoxide dismutase 1 (SOD1) cause degeneration of motor neurons in a subset of inherited amyotrophic lateral sclerosis (ALS)." (PMID 25167838, 2014). "Superoxide dismutase type 1 (SOD1) mutations cause protein aggregation and decrease protein stability, which are linked to amyotrophic lateral sclerosis (ALS) disease." (PMID 24963318, 2014).
amyotrophic lateral sclerosis (continued). "Greater than 160 missense mutations in copper-zinc superoxide dismutase-1 (SOD1) can cause amyotrophic lateral sclerosis (ALS)." (PMID 24887207, 2014). "Deficiency of miR-206 in the SOD-1 mouse model of amyotrophic lateral sclerosis (ALS) also accelerates disease progression, which is characterized by skeletal muscle atrophy from motor neuron degeneration and NMJ disruption." (PMID 24719334, 2014). "Mutations in SOD1 are causative for familiar amyotrophic lateral sclerosis, a neurodegenerative disease, due to a toxic gain of function of the mutant protein in the central nervous system." (PMID 24589581, 2014). "Microglia and reactive astrocytes accumulate in the spinal cord of rats expressing the Amyotrophic lateral sclerosis (ALS)-linked SOD1 G93A mutation." (PMID 24399933, 2013). "Amyotrophic lateral sclerosis (ALS) is a progressively paralytic neurodegenerative disease that can be caused by mutations in Cu/Zn-superoxide dismutase 1 (SOD1)." (PMID 23762114, 2013). "Dominant mutations in Cu/Zn-superoxide dismutase (SOD1) cause familial forms of amyotrophic lateral sclerosis (ALS), a fatal disorder characterized by the progressive loss of motor neurons and subsequent muscular atrophy." (PMID 23418589, 2013). "Mutations in the superoxide dismutase 1 (SOD1) gene account for more than 20 % of the familial cases of amyotrophic lateral sclerosis (ALS), an aggressive neurodegenerative disorder characterized by degeneration of upper and lower motor neurons." (PMID 24143259, 2013). "SOD1 mutations are well known in amyotrophic lateral sclerosis—a disease characterised by loss of motor neurons of the central nervous system." (PMID 24288463, 2013). "Dominant mutations in Cu,Zn-superoxide dismutase (SOD1) cause a familial form of amyotrophic lateral sclerosis (fALS)." (PMID 24348334, 2013). "Dominant mutations in a Cu, Zn-superoxide dismutase (SOD1) gene cause a familial form of amyotrophic lateral sclerosis (ALS)." (PMID 22830015, 2012). "Mutations in SOD1 cause hereditary variants of the fatal motor neuron disease amyotrophic lateral sclerosis (ALS)." (PMID 22952827, 2012). "In the present study, we use this approach to shed light on the cytotoxic action of the metalloenzyme Cu/Zn superoxide dismutase 1 (SOD1), associated with misfolding and aggregation in amyotrophic lateral sclerosis (ALS)." (PMID 22558346, 2012). "Mutation in the ubiquitously expressed cytoplasmic superoxide dismutase (SOD1) causes an inherited form of Amyotrophic Lateral Sclerosis (ALS)." (PMID 22916141, 2012). "Familial amyotrophic lateral sclerosis has been linked to mutations in the gene encoding superoxide dismutase-1, and these mutations induce misfolding and aggregation of this protein, which is believed to contribute to neuronal dysfunction and death." (PMID 21808733, 2011). "Since 1994, transgenic mice expressing high levels of mutated human SOD1 have been used as a model of amyotrophic lateral sclerosis." (PMID 21876739, 2011). "Most frequently employed is a mouse line transgenic for SOD-1 (SOD-1 Tg) that contains a point mutation at amino acid position 93 (G->A), present in patients suffering from a familial form of amyotrophic lateral sclerosis." (PMID 21102999, 2010). "Mutations of SOD1 have long been associated with the inherited form of amyotrophic lateral sclerosis (ALS) and the theory of oxidative stress-based aging." (PMID 20979611, 2010). "Examples include mutations in SOD1 (encoding superoxide dismutase 1) that cause amyotrophic lateral sclerosis and loss of function mutations in DJ-1 (encoding Parkinson disease protein 7) that leads to early onset PD with high penetrance." (PMID 20196834, 2010). "Mutations in CuZn-superoxide dismutase (SOD1) cause amyotrophic lateral sclerosis (ALS) and are found in 6% of ALS patients." (PMID 20644736, 2010).
amyotrophic lateral sclerosis (continued). "The first reports that mutations in superoxide dismutase 1 (SOD1) were causative for amyotrophic lateral sclerosis were published in 1993, and since then, over a hundred and forty mutations have been found." (PMID 20221404, 2010). "Another markedly downregulated “male-specific” gene related to oxidative stress response was SOD1, which is primarily associated with amyotrophic lateral sclerosis (ALS), but common pathways with PD have been suggested." (PMID 20111594, 2010). "Mutations in superoxide dismutase (SOD1) are the most common known cause of familial Amyotrophic Lateral Sclerosis (fALS)." (PMID 19785750, 2009). "Another enzyme with potentially important antioxidant properties is SOD1, which is implicated in certain forms of amyotrophic lateral sclerosis (ALS)." (PMID 18275612, 2008). "The central nervous system (CNS) has emerged as a crucial target area for ASO therapies, with two landmark approvals for neurodegenerative diseases: nusinersen for spinal muscular atrophy and tofersen for amyotrophic lateral sclerosis caused by the superoxide dismutase 1 (SOD1) gene mutations." (PMID 41467114, 2025). "SOD1 variants cause the motor neuron disease amyotrophic lateral sclerosis." (PMID 40957416, 2025). "Similarly, autosomal dominant mutations in SOD1 associated with amyotrophic lateral sclerosis (ALS) induce toxic protein aggregation, causing oxidative stress and neuronal apoptosis." (PMID 40964614, 2025). "This ligand is designed to bind at the SOD1 dimer interface to prevent its dissociation, a phenomenon associated with the formation of toxic monomeric species implicated in neurodegenerative diseases such as amyotrophic lateral sclerosis (ALS)." (PMID 40429802, 2025). "Amyotrophic lateral sclerosis (ALS) involves toxic SOD1 mutations." (PMID 39907846, 2025). "While this was a novel finding in the Parkinson disease field, structurally disordered (dis)SOD1 pathology has long been implicated in the degeneration of spinal motor neurons in rare inherited forms of amyotrophic lateral sclerosis (ALS) caused by SOD1 gene mutations." (PMID 40042537, 2025). "For example, disulfide-cross-linked wild-type superoxide dismutase 1 (SOD1) aggregates that are observed in amyotrophic lateral sclerosis (ALS) have been reported to accumulate in microsomes of the spinal cord during the aging of mice exposed to chronic ER stress." (PMID 41189817, 2025). "One example of this approach showed that iPSC-derived motor neurons produced from amyotrophic lateral sclerosis patients harbouring SOD1 (superoxide dismutase 1) mutations displayed a reproducible, disease-related phenotype and reduced delayed-rectifier potassium channel activity." (PMID 38397069, 2024). "For example, the researchers reported how genes traditionally associated with specific phenotypes (eg, SOD1 and amyotrophic lateral sclerosis) were presenting differently when the variant occurred in other ancestral haplotypes (SOD1 variant manifesting as FTD when present in Amerindian haplotypes)." (PMID 38801124, 2024). "Another protein that has been shown to interact with DERL1 is the mutated superoxide dismutase 1 (SOD1), which accumulates and misfolds in motor neurons in amyotrophic lateral sclerosis, another neurodegenerative disease, and the interaction with DERL1 is involved in the disease pathophysiology." (PMID 37936684, 2023). "Administration of an adeno-associated virus (AAV) vector encoding DOK7, has been shown to increase muscle strength and extended survival in models of DOK7 CMS, autosomal dominant Emery-Dreifuss muscular dystrophy, and amyotrophic lateral sclerosis due to mutations in SOD1." (PMID 36869887, 2023). "Amyotrophic lateral sclerosis (ALS), commonly called Lou Gehrig’s disease, shows selective degeneration of the upper and lower motor neurons and has been associated with genetic mutations in the enzyme Cu/Zn superoxide dismutase 1 (SOD1)." (PMID 37237691, 2023).